VDR (vitamin D receptor)
Diseases named in the same sentence as VDR in open-access papers (continued):
Sharing a sentence is not in itself a finding about the gene and the disease.
COVID-19 (continued). "Twenty-five articles have addressed the association between VDR and DBP genetic polymorphisms and treatment failure of VD in COVID-19." (PMID 37957515, 2024). "This study is one of the few studies which examined differences in the distribution of VDR SNPs between mild/moderate and severe patients with COVID-19." (PMID 38702336, 2024). "The aim of the study was the evaluation of the VDR and AhR pathways in the blood of COVID-19 patients with regard to the severity of disease." (PMID 38474725, 2024). "Low plasma levels of the vitamin D metabolite 25-hydroxyvitamin D [25(OH)D] and the vitamin D receptor (VDR) gene single nucleotide polymorphisms (SNPs) have been associated with the body’s susceptibility to infectious diseases, including COVID-19." (PMID 37049620, 2023). "The present study assessed the associations of VDR ApaI, FokI, and TaqI genotypes with the severity of symptoms experienced during SARS-CoV-2 infection and long-COVID-19 symptoms lasting over 4 weeks from the onset of infection in the Jordanian population." (PMID 38138892, 2023). "The VDR haplotype ApaI (C), FokI (C), and TaqI (T) was the major VDR haplotype in COVID-19 infected patients, as well as T2DM, T1DM patients, and healthy volunteers in Jordan." (PMID 38138892, 2023). "The VDR haplotype ApaI (C), FokI (C), and TaqI (T) with frequency of 28.2% was the most common observed haplotype among patients with COVID-19." (PMID 38138892, 2023). "Another study investigated links between COVID-19 prognosis and VDR FokI, ApaI, TaqI, and BsmI genotypes in Turkey." (PMID 38138892, 2023). "Moreover, this study might contribute to comprehending the impact of genetic polymorphisms in the vitamin D receptor with long-term symptoms that could be induced by other viruses similar to COVID-19, and help be more prepared to provide the appropriate medical care and treatment for those patients." (PMID 38138892, 2023). "Our results corroborate with a study that looked at COVID-19 patients in the Cuban population and found evidence of a relationship between SARS-CoV-2 infection and the TaqI rs731236 polymorphism in the VDR gene." (PMID 36553614, 2022). "Expression of VDR was lower in COVID-19 patients compared with controls (RME = 0.42, P value = 0.04) and in male patients compared with normal males (RME = 0.27, P value = 0.02)." (PMID 34147082, 2021). "Expression of VDR was lower in COVID-19 patients compared with controls (RME = 0.42, P value = 0.04) and in male patients compared with male controls (RME = 0.27, P value = 0.02)." (PMID 34147082, 2021). "COVID-19 patients were genotyped for variants in DHCR7/NADSYN1, GC, CYP2R1, VDR, PPCDC and DMGDH genes." (PMID 34150833, 2021). "In the current project, we have appraised expression levels of VDR, CYP27B1 and a number of associated lncRNAs in the circulation of COVID-19 patients versus healthy subjects using real-time PCR method." (PMID 34147082, 2021). "By adding data from a distinct population and variant context, our study contributes to a more comprehensive understanding of how VDR genetic variation may influence COVID-19 outcomes." (PMID 41301713, 2025). "Given that individuals with COVID-19 showed lowered expression of the VDR in peripheral blood cells, especially in male patients, the decreased sensitivities of the VDR should also be considered for evaluation of serum vitamin D concentration in patients with COVID-19." (PMID 40431432, 2025). "However, the relationship between local VDR expression and systemic vitamin D status remains inadequately explored in the context of viral infections such as COVID-19." (PMID 40904798, 2025). "The relationship between VDR SNPs and COVID-19 symptoms may differ based on the severity of the disease." (PMID 39781525, 2025). "Stimulation of VDR and corticosteroid receptors has a very similar action profile, so the combined use in patients with COVID-19 may modify the contribution of each individually." (PMID 40573079, 2025).
COVID-19 (continued). "In summary, in vivo VDR regulation in COVID-19 patients may further contribute to the well-known epidemiological link between this viral infection and following opportunistic infections." (PMID 38474725, 2024). "However, some studies have reported that dexamethasone increases the effects of 1,25-dihydroxyvitamin D3 by increasing the transcription of the vitamin D receptor, or that vitamin D and remdesivir can combat COVID-19 through a synergistic effect." (PMID 39669534, 2024). "Vit-D could activate VDR function, regulate calcium flux, reset optimal myocardial contractility, and help reduce risks of myocardial infarction in COVID-19 and PASC patients." (PMID 38555403, 2024). "This study investigates the hypothesis that COVID-19 vaccination may induce alterations in VDR mRNA expression, subsequently influencing calcium metabolism and iPTH secretion." (PMID 41717585, 2024). "Decreased VDR/PXR signaling during active infection is associated with increased systemic inflammation and increased morbidity and mortality, possibly contributing to the clinical milieu observed in severe COVID-19." (PMID 37438797, 2023). "This indicates the potential therapeutic and preventive role of vitamin D in COVID-19, which not only is responsible for calcium and phosphate homeostasis, but also has biological actions on various tissues that express the vitamin D receptor (VDR)." (PMID 36830936, 2023). "To identify the potential role of the VDR gene SNP rs2228570 in susceptibility to COVID-19, we analyzed the allele and genotype frequencies within the p-COVID-19 and no-COVID-19 groups." (PMID 37049620, 2023). "Based on this, VDR gene SNPs are considered potentially significant in the study of COVID-19." (PMID 37049620, 2023). "Thus, the binding of calcitriol and VDR activation reduce viral replication in pulmonary tissues and reduce the disease severity of COVID-19." (PMID 35892480, 2022). "Chauss and colleagues demonstrated that severe COVID-19 may result from a dysfunction of type I immune response, that involves the vitamin D receptor (VDR) signaling." (PMID 35650595, 2022). "Our study indicated an association between DHCR7/NADSYN1 rs12785878 and CYP2R1 rs10741657 variants and the severity of COVID-19, but the variants GC rs2282679 and VDR rs2228570 were not linked to a higher risk of severe COVID-19 in adults." (PMID 34150833, 2021). "Finally, the diagnostic power of VDR, CYP27B and SNHG6, SNHG16, Linc00511 and Linc00346 has been appraised in distinguishing COVID-19 patients from healthy controls and in distinguishing ICU-hospitalized patients from the other group of patients." (PMID 34147082, 2021). "Therefore, we evaluated genetic determinants of vitamin D (DHCR7/NADSYN1 rs12785878, GC rs2282679, CYP2R1 rs10741657, VDR rs2228570), zinc (PPCDC rs2120019) and selenium (DMGDH rs17823744) as risk factors for severe forms of COVID-19." (PMID 34150833, 2021). "In addition, expression of VDR was lower in COVID-19 patients compared with controls and in male patients compared with male controls." (PMID 34147082, 2021). "In this context, the stimulation of the vitamin D receptor (VDR) of the VDES has been proposed to reduce acute respiratory distress syndrome (ARDS), cardiac and coagulopathy risk, and possibly death rates in patients with COVID-19." (PMID 34064175, 2021). "The multitude of factors that affects the COVID-19 infectivity and mortality calls for adequately designed population-based prospective studies to understand the prophylactic efficiency of Vitamin D and other analogs that modulate the VDR signaling." (PMID 33551585, 2021). "In addition, activation of the VDR can promote positive effects against COVID-19, improving the antiviral response by boosting the production of antimicrobial peptides such as cathelicidin (cAMP/LL37) and β-defensin (DEFB4), as well as the modulation and induction of viral autophagy." (PMID 40573079, 2025).
COVID-19 (continued). "Importantly, VDR has also been found to play a very important role in individuals with COVID-19 in addition to vitamin D. There is growing interest in understanding how VDR and its expression may influence COVID-19 outcomes." (PMID 39781525, 2025). "Also, the vit-D supplementation could activate VDR function, regulate Ca2+ flux, reset cardiac muscle contractility, and help reduce risks of myocardial infarction in COVID-19 and PASC patients." (PMID 38555403, 2024). "However, emerging research suggests that VDR may also play a role in the context of infectious diseases, including COVID-19." (PMID 38474725, 2024). "Also, we want to try to correlate vitamin D serum levels with placental VDR expression and pregnancy outcomes in COVID-19-positive, vaccinated, and control groups, to obtain more insights into the implications of vitamin D in pregnancy, in the context of COVID-19 infection." (PMID 39458089, 2024). "By contrast, the Fok I Ff genotype showed a significant negative association with COVID-19 risk suggesting that the VDR Fok I f allele may confer protection against SARS-CoV-2 infection." (PMID 36085364, 2023). "VDES/VDR signaling may provide beneficial effects on COVID-19 by several mechanisms." (PMID 35807895, 2022). "Therefore, the observed down-regulation of VDR in COVID-19 cases might result in up-regulation of TGF-β signaling and related pathologic events." (PMID 34147082, 2021). "It is not clear whether the observed decreased level of VDR in COVID-19 is the cause or effects of COVID-19." (PMID 34147082, 2021). "In the current project, we have appraised expression levels of VDR, CYP27B1 and mentioned lncRNAs in the circulation of COVID-19 patients versus healthy subjects to unravel the role of these transcripts in the pathogenic processes during the course of COVID-19." (PMID 34147082, 2021). "Further studies are needed to address the potential role of VDR activation and DBP in the pathophysiology of COVID-19 which take into account the genetic variations of vitamin D metabolic pathway." (PMID 36830936, 2023). "Further investigations are warranted to address the potential role of VDR activation and DBP in pathophysiology of COVID-19 considering the genetic variations of the vitamin D metabolic pathway." (PMID 36830936, 2023). "Based on these and other documented effects of vitamin/VDR signaling on the local RAS, vitamin D has been touted as a potential therapeutic approach to treat ARDS of COVID-19." (PMID 34203190, 2021). "The results here also highlighted the genetic contribution of specific haplotypes for VDR, DHCR7/NADSYN1, and GC genes to COVID-19 critical condition, emphasizing the importance of genotypic variations in determining disease severity in populations." (PMID 34835935, 2021). "We, therefore, compared the VDR genotype distributions between severe influenza and COVID-19 cohorts and did not identify any significant difference." (PMID 41301713, 2025). "The results revealed that polymorphisms in the IL6, IL6R, IL1α, IL1R, IFNγ, TNFα, CRP, VDR, VDBP, and ACE2 genes are the most significant genetic factors influencing COVID-19 prognosis, particularly in terms of the risks of COVID-19 pneumonia, mortality, rehospitalization, and associated mortality." (PMID 40869297, 2025). "Interestingly, in recent studies, metformin has a beneficial therapeutic role in COVID-19 and long COVID-19, possibly by improving AMPK signaling of the VDR and enhancing the efficacy of the VD." (PMID 37957515, 2024). "The number of VDR-positive cases was higher in non-vaccinated COVID-19-negative pregnant women compared to COVID-19-positive and vaccinated ones." (PMID 39458089, 2024). "We aimed to underline a possible mechanism that would explain negative fetal outcomes in COVID-19-positive mothers by examining the relationship between altered placental structure and function and trophoblast cells’ vitamin D receptor levels." (PMID 39458089, 2024).
COVID-19 (continued). "IHC analysis revealed differences in VDR expression among the three groups, with a statistically significantly higher number of VDR-negative cases in tissue samples originating from the placenta of COVID-19-vaccinated women (p < 0.001)." (PMID 39458089, 2024). "We aim to underline a possible mechanism that would explain negative fetal outcomes in COVID-19-positive mothers by examining the relationship between altered placental structure and function and throphoblast cells‘ vitamin D receptor levels." (PMID 39458089, 2024). "Therefore, it is possible that inter-individual differences in the function of VDR and GC based on their genetic variations may have confounded the results of the clinical trials that aimed to determine the impact vitamin D supplementation on COVID-19 and other clinical outcomes." (PMID 36830936, 2023). "Considering the effects of exercise training on VDR, the combination of exercise training and vitamin D supplementation can also be effective in regulating the effects of ACE2 and preventing severe cases of COVID-19 in cancer patients." (PMID 35356739, 2022). "A transgenic murine model of COVID-19 that mimics the disease in humans is available; however, it has not been used for interventional studies of vitamin D/VDR signaling." (PMID 34203190, 2021). "However, we uncovered a higher expression of VDR in placental tissue from unvaccinated COVID-19-negative cases compared to the other two groups in our study." (PMID 39458089, 2024). "This study will also explore the potential deployment of VDR genotyping and apoptosis-related immunological and molecular assays as components of the laboratory work-up of SARS-CoV-2–infected Nigerians to further improve the quality of care of patients with COVID-19 in the country." (PMID 33621190, 2021). "However, by studying the course of COVID-19 and the immune response against SARS-CoV-2 in a family with a mutated, non-functional vitamin D receptor, we here demonstrate that vitamin D signaling was dispensable for mounting an efficient adaptive immune response against SARS-CoV-2 in this family." (PMID 34659264, 2021). "Specially, the targets of the novel CPI such as AR, VDR, CTSL and Cathepsin B (CTSB) have been reported to be relevant for the treatment of COVID-19, thus these new predicted CPIs that have not been verified are good candidates for wet experiment exploration." (PMID 35275993, 2022).
asthma (62 papers, 2005 to 2025). "Vitamin D functions through various pathways through binding to the vitamin D receptor (VDR) and its direct effects are in multiple areas such as bone health, calcium metabolism, infection risk, immune function and asthma among others." (PMID 41149648, 2025). "Its anti-inflammatory properties encompass the modulation of immune responses, particularly the regulation of pro-inflammatory cytokines linked to asthma through vitamin D receptor (VDR) signaling." (PMID 38337625, 2024). "Research also suggests that the prenatal impact of vitamin D on early-onset asthma appears to be linked to genetic variations in 17q21, the vitamin D receptor, and the vitamin D binding protein." (PMID 38846540, 2024). "The vitamin D receptor was genetically associated with asthma in 2004 and high intake of vitamin D by pregnant women is associated with about a 50% reduction in asthma risk in the mother’s offspring." (PMID 38567749, 2024). "Our findings showed that G allele of variant rs11168293 on VDR gene was more common in subjects with asthma who were found to be deficient in vitamin D than in those with vitamin D insufficiency." (PMID 37407930, 2023). "Although a previous study analyzed 13 SNPs in VDR, only the association with asthma was investigated." (PMID 37632926, 2023). "In line with our results is a study in a mixed pediatric population (n = 60 cases/17 controls, Brazil), which shows a significant association between the presence of the AA genotype in the VDR Cdx2 SNP and developing asthma (p = 0.003; AA vs. G)." (PMID 36839181, 2023). "Previous studies have evaluated the association between these variants of the VDR gene and the risk of suffering from asthma." (PMID 36839181, 2023). "The results of our study show a statistically significant association between the risk of asthma and the presence of the A allele in the VDR Cdx2 (rs11568820) polymorphism." (PMID 36839181, 2023). "We conducted the systematic review to investigate the potential relationship between the vitamin polymorphisms of D receptor (VDR) gene and childhood asthma." (PMID 35433530, 2022). "Taken together, the polymorphisms within the vitamin D receptor gene play a role in the susceptibility to asthma, and lead to an increased risk of asthma in the carriers." (PMID 36292755, 2022). "GWAS has identified four single nucleotide polymorphisms within the VDR gene that are shown to be related to asthma risk and severity." (PMID 36292755, 2022). "Relevant studies researching on VDR polymorphisms and asthma susceptibility were searched throughout Embase, PubMed, China Science and technology journal database (CQVIP), etc. till 12 April, 2021." (PMID 35433530, 2022). "Looking at the link to asthma specifically, the association between a number of VDR restriction fragment length polymorphisms and the risk of asthma has been described." (PMID 35625670, 2022). "Recently, accumulating evidence researched the function role of VDR gene polymorphism in childhood asthma, and four SNPs, including BsmI (rs1544410), ApaI (rs7975232), FokI (rs2228570), and TaqI (rs731236), were the main gene locuses." (PMID 35433530, 2022). "A different report in the Turkish Cypriot adolescent population showed that TaqI homozygous minor genotype of the VDR gene was linked with asthma." (PMID 34343413, 2021). "In childhood asthma, vitamin D levels act as a possible marker for disease severity via the VDR Apal A/a genotype which was positively associated to well-controlled asthma." (PMID 33801051, 2021). "Another study on vitamin D levels, VDR polymorphisms, and asthma was performed in Salvador, Northeast Brazil children." (PMID 34343413, 2021). "Children carrying the C allele for TaqI were more likely to develop asthma, and interleukin-10 levels were significantly low in asthmatics with the TC genotype for TaqI due to a decrease in expression of VDR." (PMID 33633666, 2021).